SGK1 (serum/glucocorticoid regulated kinase 1)
Diseases named in the same sentence as SGK1 in open-access papers (continued):
Sharing a sentence is not in itself a finding about the gene and the disease.
tumor (continued). "The survival analysis indicated that high expression of both ClC-3 and SGK1 was associated with poor survival rate in STAD patients, suggesting that ClC-3 and SGK1 might be tumor-promoting factors in STAD development." (PMID 33093458, 2020). "In studies of several tumor types, the expression and function of SGK1 are quite different." (PMID 33542904, 2020). "SGK1 knockdown in tumor cells can lead to lower levels of β-catenin." (PMID 33266470, 2020). "Several inhibitors of SGK1 have shown great potential in inhibiting tumor metastasis." (PMID 33542904, 2020). "In conclusion, our data suggest that PPARβ/δ is a tumor suppressor in HCC and that downregulation of SGK-1 may be implicated in its tumor-suppressive effect." (PMID 33083492, 2020). "SGK1 supports cell survival and cell proliferation of both tumor cells and neurons." (PMID 31225494, 2018). "This study highlights a novel and pivotal role for SGK1 in tumor metastasis." (PMID 29609629, 2018). "SGK1 may support survival of tumor cells by counteracting apoptosis via phosphorylation, and thus inhibits glycogen synthase kinase 3, which downregulate oncogenic β-catenin." (PMID 26942879, 2016). "However, expression of SGK1 was increased significantly in GC compared with both tumor adjacent tissues and normal tissues." (PMID 26942879, 2016). "This selective behavior could reflect a different level of expression and/or activation of SGK1, together with a different metabolic condition between tumor and healthy cell models (e.g. chronical stress and oxidative bursting)." (PMID 26908461, 2016). "Similar to Akt1, SGK1 is highly expressed in a wide variety of tumor cells." (PMID 25015419, 2014). "In addition, SGK1 is highly expressed in tumor cells and it phosphorylates EP300 to acetylate NF-kB and is downregulated by ubiquitination via NEDD4-2." (PMID 25520040, 2014). "The results of the present study suggest that monitoring SGK1 levels as well as responses of NDRG1 phosphorylation to Akt inhibitor administration could have a use in predicting the sensitivity of tumours to compounds that target Akt." (PMID 23581296, 2013). "We advocate that monitoring NDRG1 phosphorylation responses following administration of Akt inhibitors could represent an effective general biomarker to assess SGK1 activity in tumour cells." (PMID 23581296, 2013). "Such tumours might be better treated with signal transduction suppressors that reduce SGK1 activity, such as mTOR inhibitors." (PMID 23581296, 2013). "In future studies it would be important to establish whether potent and selective inhibitors of SGK1 would inhibit proliferation of tumour cells displaying elevated SGK1 activity." (PMID 23581296, 2013). "Akt-inhibitor-resistant tumours displaying elevated SGK1 might be better treated with mTOR inhibitors that suppress SGK1 activity." (PMID 23581296, 2013). "Down-regulation of the SGK1 transcript was confirmed in all tumour samples by qRT-PCR." (PMID 21079778, 2010). "Notably, many tumor cells exhibit elevated SGK1 expression levels." (PMID 41326907, 2025). "Furthermore, inhibition of SGK1 has demonstrated potent anti‐tumor effects." (PMID 41326907, 2025). "Moreover, SGK1 expression in 4T1 orthotopic tumor tissue was also augmented after Dex treatment." (PMID 34272474, 2021). "Additionally, tumor weight was markedly increased after SGK1 silencing." (PMID 33517828, 2021). "Thus, SGK1 impacts a wide variety of physiological functions and plays an active role in the pathophysiology of several disorders, including hypertension, diabetes, inflammation, autoimmune disease, and tumor growth." (PMID 33542904, 2020). "Therefore, SGK1 downregulation contributes to tumor rejection via blocking TCF-1 signaling." (PMID 33542904, 2020). "Finally, we characterized how combined Src and SGK1 targeting affected tumor growth in vivo." (PMID 30655532, 2019).
tumor (continued). "These comprised two truncating pathogenic variants—RB1 R255* and TSC1 R786*, one missense probable damaging variant—VHL tumor suppressor R58W, and four splice variants of unknown significance in ETS2 transcription factor, SGK1 serum/glucocorticoid regulated kinase 1, AXL RTK and MIB1." (PMID 31258848, 2019). "Thus, an important conclusion from our studies is that MNK inhibitors may be more widely applicable for tackling tumour metastasis than inhibitors of SGK1." (PMID 28545025, 2017). "In preclinical models, SGK1 knockout mice had increased response to tumor immunotherapy compared to mice with functional SGK1, suggesting that mTOR up-regulation dampens or inhibits anti-tumor immunity (unpublished data from Dr. Jonathan D. Powell, Johns Hopkins University)." (PMID 24829749, 2013). "We prioritized FKBP5 (HP pharmacodynamics) and CLDN4 (tumor baseline) as the main candidates; TSPO and SGK1 are reported as exploratory." (PMID 41614938, 2026). "It regulates key pathways such as AKT/mTOR, cytochrome c/caspase, and SGK1-FOXO3a-BNIP3, influencing tumor cell proliferation, metastasis, apoptosis, and autophagy." (PMID 40259338, 2025). "Lactate can upregulate the expression of SGK1 through demethylation mediated by TET2, enhancing the immunosuppressive function of MDSCs to promote tumor progression." (PMID 40917754, 2025). "UMAP clustering identified different triple-negative tumour cell clusters which were characterized by migration and GR signature and by NR3C1, and GR target SGK1 and TSC22D3 gene expression." (PMID 39905197, 2025). "While overexpressed SGK1 and LOX1 were found in the tumor and adjacent to the tumor in liver specimens from patients with CRLM." (PMID 36788538, 2023). "Collectively, our experimental data demonstrated that PDCD5 harbored tumor-suppressive property by inhibiting the proliferation of RCC cells and enhancing the immune functions of T cells via the HDAC3/miR-195-5p/SGK1 axis." (PMID 36266728, 2022). "Next, in in vivo study, by analyzing the protein levels of SGK1 and CTGF in tumor tissues of mice bearing tumor, similar effects were also observed in different groups." (PMID 33517828, 2021). "In gastric tumors, overexpression of the SGK1 target, NDRG1, is suggested to stimulate IL-1 expression and induce tumor angiogenesis through JNK/AP-1 activation." (PMID 35250965, 2021). "Sgk1 phosphorylates downstream NDRG1 and is involved in regulating tumor cell proliferation, differentiation, migration, and invasion." (PMID 32106831, 2020). "A significant positive correlation was also detected between post-NAC Sgk1 and NDRG1 status of the tumor tissues (P = 0.0009)." (PMID 32106831, 2020). "Rictor inhibition in pancreatic cancer leads to impaired tumour growth and phosphorylation of AGC kinases, including SGK1." (PMID 29301334, 2018). "In this respect we found that expression of SGK1 (also an AGC kinase) is impaired upon RICTOR blockade, which is likely related to the impairment in IL-8 secretion from tumor cells." (PMID 28445935, 2017). "Indeed, our previous experiments had already shown that the individual distribution of AKT kinases and SGK-1 differ between individual tissues, which might explain why shc-1;akt-1 germline tumor are potently suppressed by RNAi down-regulation of either akt-2 or sgk-1." (PMID 28549065, 2017). "It is therefore likely that in tumours displaying activated PI3K signalling, both Akt1/2 and SGK1/SGK2 would be elevated and stimulate proliferation by phosphorylating an overlapping subset of substrates." (PMID 27481935, 2016). "Consistent with knock-down and over-expressing cellular models for SGK1, SI113 potentiated and synergized with radiotherapy in tumor killing." (PMID 26462020, 2015). "The serum glucocorticoid-regulated kinase-1 (SGK-1), a serine-threonine kinase well known for the regulation of renal sodium transport, has been described to support survival of tumor cells." (PMID 25485633, 2014).
tumor (continued). "Like AKT isoforms, SGK1 does not appear to be mutated in human AML, as expected if the gene acts as a tumor suppressor." (PMID 40613901, 2025). "In conclusion, we revealed a novel target of SGK1 in the regulation of the immunosuppressive function of MDSCs by lactate, and clarified the important role of TET2-mediated SGK1 demethylation in anti-tumor immunity." (PMID 40917754, 2025). "One particular GR target gene, serum and glucocorticoid-regulated kinase 1 (SGK1) has been shown to have a prominent role in ENZ resistance; inhibition of SGK1 decreased PCa cell viability, while its overexpression increased tumor initiation." (PMID 34137734, 2021). "Ligation of Dex and glucocorticoid receptor (GR) on tumor cells activated the PI3K signaling pathway and upregulated serum glucocorticoid-inducible kinase 1 (SGK1) expression, and then increased the expression of connective tissue growth factor (CTGF) through Nedd4l-Smad2." (PMID 34272474, 2021). "Intriguingly, through injecting KYSE-30 cells with OV-TEAD4 transfection or in combination with shRNA-SGK1 transfection into nude mice, we found that SGK1 silencing markedly interfered with the effects of TEAD4 overexpression on tumor volume and the expression of Ki67 and MMPs (MMP2 and MMP9)." (PMID 33517828, 2021). "The expression pattern of SGK1 has been extensively investigated and compared in nontumor and tumor human tissues." (PMID 33542904, 2020). "Results from our present study indicate that NDRG1 was activated via Sgk1 in ESCC undergoing NAC and thus could be involved in the local progression of the tumor." (PMID 32106831, 2020). "The status of GR was significantly correlated with the presence of vessel invasion (P = 0.016), that of Sgk1 with pT (P = 0.006) and pN (P < 0.001), pStage (P < 0.001), lymphovascular invasion (P = 0.003), RECIST grade (P = 0.007), and histopathological tumor regression grade (P = 0.037)." (PMID 32106831, 2020). "The relevance of SGK1 to the SFK signaling network in TNBC was confirmed by its increased expression in this disease subtype together with its positive regulation by Src in TNBC cells and contribution to colony formation in vitro and tumor growth in vivo." (PMID 30655532, 2019). "Furthermore, the three AGC kinases AKT-1, AKT-2, and SGK-1 that in most previous studies have displayed redundant activities as negative regulators of DAF-16, have antagonistic roles in DAF-16 mediated tumor formation." (PMID 28549065, 2017). "Since SGK1 inhibition increased, whereas SGK1 over-expression decreased the sensitivity to oxidative stress, we conclude that SGK1 expression appears essential and rate-limiting in the modulation of the oxidative response in GBM tumor models." (PMID 26908461, 2016). "Given that SGK1 plays a role in controlling cell proliferation by suppressing FoxO3a function, deregulation of SGK function may be involved in tumor growth." (PMID 24558442, 2014). "In contrast, tumours displaying elevated SGK1 mRNA/protein in which NDRG1 phosphorylation is not suppressed by Akt inhibitors are likely to be more resistant to Akt inhibitors." (PMID 23581296, 2013). "Our results show that even though partial methylation of the promoter region of SGK1 is present, this does not account for the different expression levels seen between normal and tumour tissue." (PMID 21079778, 2010). "Further confirmation that down-regulation of SGK1 in tumour samples is not highly dependent on promoter hypermethylation, was obtained by treating the CRC cell lines with 5-AzaC, an inhibitor of methylation." (PMID 21079778, 2010).
tumor (continued). "We speculated that non-parenchymal cells other than hepatocytes expressing SGK1 contributed to the inflammatory progression of hepatic IR and IR-exacerbated tumor metastasis." (PMID 36788538, 2023). "Collectively, SGK1 expression was upregulated by the PI3K pathway activated by ligation of Dex and GR, and then SGK1 phosphorylated Nedd4l, which led to Smad2 release from the suppressive Nedd4l-Smad2 complex, and subsequent upregulation of CTGF, which finally promoted tumor metastasis." (PMID 34272474, 2021). "In addition, Although T cell Lnc-SGK1 expression was related to tumor size and metastasis, Lnc-SGK1 alone was not sufficient to determine the prognosis of GC." (PMID 26942879, 2016). "The results showed that, although GSK650394 could inhibit SGK1 expression in vivo, it did not affect tumor growth or weight, whereas the number of metastases on the lung surface in the Dex+GSK group was significantly decreased compared with that in the Dex-only group." (PMID 34272474, 2021). "However, this region was also found to be methylated in normal colonic tissue and therefore is unlikely to account for the differences in SGK1 expression seen between normal and tumour tissue samples, which are instead most likely due to transcriptional repressors acting on the SGK1 promoter." (PMID 21079778, 2010).
infection (17 papers, 2013 to 2025). The state of being infected such as from the introduction of a foreign agent such as serum, vaccine, antigenic substance or organism. "In this context, SGK1 inhibition also aggravated bone loss in Pg-infected mice, possibly suggesting that SGK1 is a negative regulator of inflammation in infection." (PMID 36457711, 2022). "Importantly, re-expression of SGK1 by infection of an adenovirus encoding CA-SGK1 rescued formation of tube networks." (PMID 24265802, 2013). "Importantly, re-expression of SGK1 by infection of ECs with an adenovirus encoding the constitutively active form of SGK1 re-established tube networks compared to KO ECs infected with control virus expressing βGal." (PMID 24265802, 2013). "aeruginosa LPS35 and Toxoplasma gondii, the present study has further underscored the role of augmented SGK1 phosphorylation as a consequential response to pathogen infection in modulating immune and inflammatory responses." (PMID 38528022, 2024). "Stress can directly stimulate SGK1 levels as well as stimulate herpes simplex virus 1 (HSV-1) productive infection and reactivation from latency." (PMID 39205282, 2024). "Our results found that the SGK1 activity was up-regulated at 4 and 24 h post-infection, and the CFTR inhibitors, Glyh-101, CFTRi-172, and IOWH-032, attenuated the SGK1 activity in infected cells." (PMID 39205282, 2024). "Taken together, these results demonstrated that infection with P. gingivalis activates SGK1 in innate cells." (PMID 35588785, 2022). "Like the phosphorylation of SGK1, infection of P. gingivalis indeed elevated phosphorylation of NDRG1 at threonine 346/356/366 in all cells we investigated." (PMID 35588785, 2022). "Induction of SGK1 mRNA expression in A549 cells was greater still, reaching ~10-fold increase at 36 h post-infection." (PMID 30367157, 2018). "Protein expression of SGK1 followed the same trend as seen with the MR, where expression increased during infection, but overall levels were lower in cells depleted for the MR." (PMID 30367157, 2018). "The up-regulation of SGK1 expression via a lentiviral-mediated approach resulted in a different expression pattern (72 h after infection), characterized by a net increase in both the mature and precursor miRNA forms." (PMID 28358001, 2017). "Inhibition of SGK1 was performed using lentiviral SGK1-shRNA infection in Ben-Men-1 cells, or with the SGK1 inhibitor GSK650394 in both Ben-Men-1 cells and NF2-shRNA ACs." (PMID 26219339, 2015). "MA10 infection induced six down-regulated (Pllp, Malat1, Myrf, Mag, Ptgds, Ugt8a) and two upregulated DEGs (Sgk1, Mbp), while Aβ pathology resulted in one down-regulated (Hmgb1) and ten up-regulated DEGs (Apoe, B2m, Clu, Cstd, Gfap, Psen1, Pllp, Cst7, Cd9, Plp1)." (PMID 41497643, 2025). "At the time of infection, cells were also treated with various concentrations of SGK1 inhibitors 5377051 and 6410136, two of the molecules identified from the second-generation CADD-generated screen and validated as SGK1 inhibitors in the in vitro kinase assay." (PMID 28336914, 2017). "Thus, expression of LINC00968, LINC01105, lnc-SGK1, MHRT, MIR17HG, and NeST were only or largely impacted in GPHT infection." (PMID 31547203, 2019). "SGK1 and Lnc-SGK1 expression in peripheral T cell of patients with H. pylori infection (Hp Pos., 187 cases) was higher than in those without infection (Hp." (PMID 26942879, 2016).
metabolic disorders (7 papers, 2015 to 2025). "This multi-target regulation provides a theoretical foundation for understanding the function of SGK1 in tumorigenesis, metabolic diseases, and inflammation-related pathological processes." (PMID 40427579, 2025). "Inhibition of SGK1 is considered as a valuable approach for the treatment of various metabolic diseases." (PMID 35955763, 2022). "EMD638683 reverses glucose absorption in a mouse model, suggesting that SGK1 may serve as a therapeutic target in metabolic disorders." (PMID 35222400, 2022). "Castration further leads to glycolipid metabolic disorders and increased expression of inflammatory cytokines by affecting the expression of HSD11B1, SGK1, PCK1, and SLC2A4 in abdominal adipose tissues and their regulatory factors." (PMID 35456474, 2022).
cardiovascular disease (6 papers, 2020 to 2023). "However, there are still many unanswered questions about the associations and interactions between these DEGs and SGK1 in nerve cells and cardiovascular diseases, which, although having been studied, require further research." (PMID 37371111, 2023). "This will contribute to a better understanding of the role of SGK1 in the regulation of the nervous system and to future research on neuromodulation in cardiovascular diseases." (PMID 37371111, 2023). "The results of this study show that SGK1 function is not only related to nerve growth and development but also that SGK1 in nerve cells may be related to cardiovascular regulation and cardiovascular diseases." (PMID 37371111, 2023). "Moreover, SGK1 inhibition may have additional protective effects during cardiovascular disease progression." (PMID 33003561, 2020). "In atherosclerotic cardiovascular diseases, increased intracellular Cl- concentration in neutrophils promotes NET formation via Cl–sensitive SGK1 signaling." (PMID 36532016, 2022). "However, current research on whether SGK1 is involved in cardiovascular diseases is lacking." (PMID 37371111, 2023).
Kidney Diseases (6 papers, 2015 to 2025). "Its pleiotropic role in kidney disease is further supported by the fact that SGK1 is associated with aldosterone-induced oxidative stress and podocyte injury." (PMID 34064989, 2021). "The DO analysis in this study showed that SGK1 inhibition-induced DEGs in PC12 cells were associated with cranial, nervous, and renal diseases." (PMID 37371111, 2023). "SGK1 has been shown to contribute to the pathophysiology of several disorders, including cardiac remodeling, hypertension, stroke, diabetes mellitus, kidney disease, or inflammation." (PMID 30706178, 2019). "Moreover, SGK1 inhibition may potentially have an overall protective effect during cardiovascular or renal disease progression." (PMID 30706178, 2019).
neurodegenerative disease (6 papers, 2019 to 2026). A disorder of the central nervous system characterized by gradual and progressive loss of neural tissue and neurologic function. "The activation of the NRLP3‐inflammasome has lately been reported as a central pathogenic contributor to neurodegenerative diseases, including AD and PD, further indicating that SGK1 inhibition in glia could be a therapeutic intervention for those disorders." (PMID 33646633, 2021). "While there have been numerous studies on SGK1 in neuronal tissues and cells, the majority of them have focused on research related to neurodegenerative diseases." (PMID 37371111, 2023).